FGFR3 (fibroblast growth factor receptor 3)
Diseases named in the same sentence as FGFR3 in open-access papers (continued):
Sharing a sentence is not in itself a finding about the gene and the disease.
tumor (continued). "FGFR3 was mutated in 2/17 primary tumours of patients with recurrence, and 3/18 patients without recurrence, with one mutation (Ser249Cys) accounting for 4/5 of the mutations and the remaining mutation being adjacent (Arg248Cys)." (PMID 35008243, 2021). "Using univariable analysis, we then found that the tumor grade (HR = 571.72 [11.03–2.96] p = 0.002), PD-L1 expression (HR = 2.33 [0.92–1.92] p = 0.012), and FGFR3 expression (HR = 0.08 [0.17–0.42] p = 0.003) were significantly associated with relapse-free survival." (PMID 33238591, 2020). "Additionally, these compounds presented potent inhibition against the tumor growth-related tyrosine multiple kinase targets FGFR3, IGF1R, PDGFRb, and TRKB at a concentration of <10.4 μM, except for 151, which showed weak activity, with IC50 > 25 μM." (PMID 32570903, 2020). "In contrast, FGFR3 mutations seem to be rare in mixed LNUC, which may indicate a different pathway of tumor development." (PMID 32213857, 2020). "Most of the FGF9‐positive tumours exhibited also elevated FGFR3‐IIIb or FGFR3‐IIIc." (PMID 32378800, 2020). "The loss of FGFR3 is significantly associated with higher grade urothelial bladder tumors and also leads to chondroma-like lesion formation by downregulating ERK signaling whilst upregulating Hedgehog signaling, suggesting tumor suppressive roles of FGFR3." (PMID 31987043, 2020). "Sensitivity was defined as the ability of the MASO-PCR assay to detect FGFR3 mutations (+) and specificity as the ability of assay to identify the absence of FGFR3 mutations (−) in primary NMIBC tumor (diagnosis) as well as recurrence (follow-up)." (PMID 32448160, 2020). "FGF/FGFR3 axis may induce carcinogenic effects by promoting cancer progression and increasing angiogenesis potential, leading to metastatic tumor phenotypes." (PMID 33381388, 2020). "FGFR3 was also a poor prognostic factor and promoted tumor angiogenesis." (PMID 32795296, 2020). "Compounds 460–462 showed strong cytotoxicity against six HTCLs (HCT-116, HepG2, BGC-823, NCI-H1650, A2780, and MCF7) (IC50 = 1.3–12.5 μM) and exhibited selective significant inhibitory activity towards the human tumor-related protein kinases of FGFR3, IGF1R, PDGFRb, and TrKB (IC50 = 2.6–21.4 μM)." (PMID 32570903, 2020). "Indeed, FGFR3 was the second highest differentially expressed gene between invasive and tumor core GBM cells." (PMID 31337028, 2019). "In the MCC xenografts mice, knockdown of FGFR3 decreased tumor growth and metastasis." (PMID 31619201, 2019). "FGFR TK family (FGFR1, FGFR2, FGFR3, and FGFR4) members encode transmembrane proteins that contain immunoglobulin-like and kinase domains that play diverse roles in controlling cell proliferation, cell differentiation, angiogenesis, and tumor development." (PMID 31007851, 2019). "Also, if we compare this to current detection methods for TERTp and/or FGFR3 based on Sanger sequencing, the high increase in sensitivity is a key factor, especially since we are trying to detect trace amount of tumor cells in urine samples." (PMID 31921291, 2019). "FGFR3 protein expression was dramatically higher in tumor (T) than in normal (N) samples." (PMID 29850625, 2018). "This might point towards the fact that FGFR3 overexpression may also evolve during tumor progression under treatment." (PMID 30181810, 2018). "Among 74 tumor samples tested, we found 16 (22%) actionable FGFR3 gene aberrations." (PMID 30064409, 2018). "This increase in inflammation was mainly associated with overall tumour progression rather than FGFR3 mutations." (PMID 30043421, 2018). "Firstly, we assume that the increased frequency of rs798766[T] may implicate directly to the regulatory region and enhance the promoter activity of FGFR3, triggering subsequent overexpression of FGFR3 gene which ultimately induces the transformation to tumor." (PMID 28655970, 2017). "This further suggests that higher FGFR3 expression is not directly linked to young patient age or pediatric tumor type." (PMID 28468611, 2017).
tumor (continued). "Expression of both FGFR1 and FGFR3 varied within all tumor types." (PMID 28468611, 2017). "We also identified one tumor that expressed an FGFR3-CAT fusion transcript." (PMID 28636652, 2017). "The clinical significance of FGFR3 protein expression differs somewhat among tumor types." (PMID 28056982, 2017). "Indeed, patients with age < 20 years at tumor onset had a higher frequency of FGFR3 immunopositive staining (p < 0.05, Fisher’s exact test)." (PMID 28468611, 2017). "However, the mRNA expression of FGFR2 and FGFR3 was comparable between tumor and paired normal tissue." (PMID 26936993, 2016). "We analysed the FGFR3 exons 7, 10 and 15 in tumor DNA derived from evaluable 91 RPC patients." (PMID 27029078, 2016). "Moreover, FGFR3 was significantly negatively correlated with cell cycle, which indicated active mitosis and proliferation of tumor cells." (PMID 27829236, 2016). "bFGF is able to bind FGFR1, FGFR2, and FGFR3, leading to auto-phosphorylation of intracellular tyrosine residues, which are involved in instigating tumor cell proliferation and invasion in various tumor types." (PMID 26824699, 2016). "Tumor size > 3cm correlated with FGFR3 fusions independently in multivariate modeling." (PMID 27409839, 2016). "The prognostic value of FGFR3 protein expression seems to be tumor‐type dependent." (PMID 26711175, 2016). "Because FGFR3 is a known HSP90 client protein we treated tumor stromal fibroblasts with STA-1474." (PMID 26560147, 2015). "Therefore, in the present study inhibiting FGFR3 or eIF4E selectively suppressed the expression of FGFR3 or eIF4E regulated proteins and substantially repressed tumor growth on tumor models." (PMID 26078354, 2015). "Through clinicopathologic analysis, we also found that patients with oncogenic FGFR3 mutations were characterized by male, smokers, and larger tumor size without mediastinal lymph node metastasis." (PMID 26486077, 2015). "It was shown that FGFR3 signal can limit tumor growth with epithelial origin." (PMID 25469175, 2014). "On the basis of our findings, we believe that the importance of FGFR3 as a driver of tumor growth and progression in metastatic UC is unclear, and further functional evidence is required to support this hypothesis." (PMID 24846059, 2014). "In this context, miR-100 could be considered as a tumor suppressor miRNA because it regulates the activity of the tyrosine kinase receptor FGFR3." (PMID 25493074, 2014). "This was not a reflection of tumor purity, as all mutation-negative specimens had comparable tumor cellularity by histopathologic assessment (80-95%) and identical allele fractions of common SNPs in FGFR3 and PDGFRA (≥99%, data not shown)." (PMID 25523272, 2014). "FGFR3 can have both tumor suppressive and oncogenic properties." (PMID 25469175, 2014). "The new hypothesis that FGFR3 can harbor both tumor suppressive and oncogenic properties is crucial in the context of targeted therapies involving specific tyrosine kinase inhibitors (TKIs)." (PMID 23902722, 2013). "In a recent study, FGFR3 mutation status was found to be predictive of progression, recurrence, and outcome only when combined with 9p22 LOH status, but this was in a relatively small sample set, including only 29 FGFR3-mutant tumours." (PMID 22899908, 2012). "In addition, the member genes FGF19, GAS2, BMP7, TNFSF11, and FGFR3 are all known to play important roles in tumor genesis and progression." (PMID 22863767, 2012). "Overexpressed FGFR3 could contribute to tumour development by either ligand-dependent or independent mechanisms." (PMID 22899908, 2012).
tumor (continued). "In this study we therefore considered two pathways: the FGFR3-mutated tumor pathway and the FGFR3-non-mutated tumor pathway." (PMID 22724020, 2012). "We chose to filter the Pearson correlation values with the threshold: |r| >0.479 (pVal <1%) for the Ta G1/G2 (FGFR3-mutated) tumor group and |r| >0.323 (pVal <1%) for the T2–4 (FGFR3-non-mutated) tumor group." (PMID 22724020, 2012). "Thus, the silencing phenotype is specifically associated with CIS, high tumor grade and stage, MIBC development and very low frequency of FGFR3 mutations." (PMID 23372425, 2012). "for each deregulated gene, a specific association either with the FGFR3-mutated tumor group or the non-mutated tumor group was investigated as well as an association with a differentiation or proliferation phenotype." (PMID 22724020, 2012). "We expected to find more genes linked to differentiation being lost in the FGFR3-non-mutated tumor pathway as these tumors are usually of high grade compared to the tumors of the FGFR3-mutated tumor pathway." (PMID 22724020, 2012). "We selected the genes found significantly up- or down- regulated only within the FGFR3-non-mutated tumor pathway or within the FGFR3-mutated tumor pathway." (PMID 22724020, 2012). "Preliminary results show that a combined test for mutation of FGFR3, PIK3CA and RAS could potentially detect 75% of primary tumours, including 88% of the pTa-T1G1-2 tumours but only 36% of the high-grade and -stage malignancies." (PMID 22899908, 2012). "Only one tumor in these two subgroups harbored an FGFR3 mutation and no overexpression of FGFR3 was observed." (PMID 22685613, 2012). "This suggests a possible neuroendocrine differentiation in the FGFR3-non-mutated tumor pathway that would not be present in the FGFR3-mutated tumor pathway." (PMID 22724020, 2012). "The FGFR3-non-mutated tumor pathway comprised the TaG3 FGFR3-non-mutated tumors, the T1 FGFR3-non-mutated tumors and the muscle-invasive FGFR3-non-mutated tumors." (PMID 22724020, 2012). "However, overall sensitivity is around 80%, as it is limited by the fact that around one-fifth of patients with an FGFR3-mutant primary tumour have FGFR3 wild-type recurrences." (PMID 22899908, 2012). "FGFR3 activation concurrently contributes to cell survival of Ctx-naive EGFR ligands-positive SCC tumour cells challenged to Ctx at first, thus limiting its activity and likely promoting their own resistance if Ctx-induced blockade of EGFR-ligands signalling persists." (PMID 22491422, 2012). "(fibroblast growth factor receptor 3) is induced in lymphatic endothelium by its developmental "master switch" Prox1, and it plays a role in the biology of lymphatics which are important in inflammation and tumor biology." (PMID 21223544, 2011).
tumor (continued). "We screened the bulk of tumour present in three additional ISS cases for activating mutations in FGFR3 and HRAS, but no sequence variations were identified in these samples." (PMID 21706474, 2011). "We demonstrate that FGFR3 mutation analysis on voided urine is a simple non-invasive method and could serve as a feasible follow-up approach for this young patient presenting with an FGFR3 mutant tumor." (PMID 20187926, 2010). "This receptor may have a major impact on tumour cell characteristics because of its broad ligand spectrum (FGFs 1, 2, 4, 6, 9 and 18) compared with FGFR3-IIIb (FGFs 1 and 9 exclusively)." (PMID 20234367, 2010). "Single FGFR3-positive cells have the potential for tumour formation in vivo." (PMID 19888223, 2009). "Six of six tumours formed by FGFR3+ cells inoculated into mice formed tumour." (PMID 19888223, 2009). "The 4 patients with S249C FGFR3 mutation tumor were significantly older at time of diagnosis than patients without the S249C FGFR3 mutation in the tumor (mean age 64 vs. 49.4 years, P = 0.02, Mann-Whitney U test)." (PMID 15869706, 2005). "They found that patients with intense FGFR3 immunolabeling in tumor cells had a better prognosis." (PMID 15869706, 2005). "Furthermore, some studies have suggested distinct clinicopathological characteristics of FGFR3-fused NSCLC including more frequent association with smoking, significantly larger tumor size, and more frequent poor differentiation than those without FGFR fusions." (PMID 39387893, 2025). "Tumours harbouring FGFR3 alterations may benefit from FGFR inhibitors." (PMID 41375830, 2025). "Luminal tumours exhibited an expression pattern similar to the intermediate/superficial layers of the urothelium, frequently activating PPAR target genes and showing a higher incidence of mutations in FGFR3, ELF3, CDKN1A, and TSC1, as well as overexpression of proteins such as E-Cad, HER2/3." (PMID 39594166, 2024). "In FGFR3 altered patients, the tumor immune microenvironment (TIME) has been found to have a generally non-T cell inflamed phenotype, but also relatively low immunosuppressive stromal features, which may allow a subset of patients to be responsive to ICI therapy." (PMID 36806983, 2023). "These two distinct tumor types might display FGFR3::TACC3 fusion." (PMID 36647073, 2023). "OPCML exerts its tumor suppressor effect by inhibiting several cancer hallmark phenotypes in vitro, and abrogating tumorigenesis in vivo, by downregulating/inactivating a specific spectrum of Receptor Tyrosine Kinases (RTKs), including EphA2, FGFR1, FGFR3, HER2, HER4, and AXL." (PMID 36835855, 2023). "Notably, a total of 10 previously reported single-nucleotide polymorphisms (SNPs) were found in this tumor in genes including MLH1 (rs769364808), FGFR3 (rs769364808), two variants (rs1873778 and rs2228230) in PDGFRA, KIT (rs55986963), APC (rs41115), and RET (rs1800861)." (PMID 37273678, 2023). "While there is a slightly higher tumor mutational burden in EPAS1-altered tumors (9.9 vs. 4.9 mut/Mb), they are enriched in and associated with genes promoting immune evasion, including ARID5B, SPINT1, AAK1, CLIC3, SORT1, SASH1, and FGFR3, respectively (q < 0.001)." (PMID 36421334, 2022). "Since UTUC metachronous MIBC has higher FGFR3 expression compared with primary bladder MIBC, it suggests that MIBC following UTUC may take over FGFR3 expression from UTUC tumor origin, which may have resulted in favorable survival outcomes with additional RC compared to that of bladder primary MIBC." (PMID 35563543, 2022).
tumor (continued). "Overall, how altered FGFR3 functions to affect tumor biological behaviors and survival of BC patients is still unclarified, and whether FGFR3 alterations related to molecular mechanisms correlated with the prognosis and treatment response in BC merits further investigation." (PMID 35958598, 2022). "We performed DNA methylation analysis of the encoding genes FGFR1, FGFR2, FGFR3, FGFR4, FGF1-14, FGF16-23, and CCND1 at single CpG site resolution (840 CpG sites) employing The Cancer Genome Research Atlas (TCGA) HNSCC cohort comprising N = 530 tumor tissue and N = 50 normal adjacent tissue samples." (PMID 34933671, 2021). "Furthermore, the experiments described here use a tumor cell line that is not dependent on the FGFR3 activating mutation, which was exogenously introduced." (PMID 34984415, 2021). "This discordance between in vitro and in vivo data may be caused by the fact that the oncogenicity of FGFR3 R248C was not as high as the other variants, and the tumor growth was slow." (PMID 34272467, 2021). "Therefore, FGFR3-targeted therapies can be effective in reducing tumor angiogenesis." (PMID 32795296, 2020). "However, multivariate analysis revealed that FGFR3 p.R248C is not independently associated with tumor size." (PMID 32023888, 2020). "Moreover comprehensive DNA sequencing analyses identified the FGFR3 amplification in the tumor." (PMID 32252664, 2020). "A negative correlation was also between the FGFR3 mutations and tumor stage (p = 0.002)." (PMID 32397531, 2020). "In addition, FGFR1 was expressed on iCAFs and ECs, while FGFR3 was expressed on tumor cells." (PMID 33033240, 2020). "However, in bladder cancer, APOBEC-low expressing tumours often present mutations in FGFR3 and RAS family of oncogenes; whereas APOBEC-high expressing tumours usually have mutations in DNA damage response genes and chromatin regulatory genes, an enhanced immune response and better overall survival." (PMID 31547885, 2019). "However, the correlation between FGFR3 and tumor progression, coupled with the underlying mechanisms, are not fully understood." (PMID 29850625, 2018). "Here, we show that FGFR3-dependent tumors are sensitive to tubacin, tubastatin A and HDAC6 deficiency and reveal unique, HDAC6-independent activities of tubacin that may contribute to its superior ability to block tumor growth." (PMID 29423038, 2018). "Finally, combining FGFR3 mutational status with methylation measurement of a set of DNA methylation markers (HS3ST2, SEPTIN9 and SLIT2) led to a sensitivity/specificity/NPV of 94.5/75.9/98.5%, respectively, for detection of a recurrent tumor." (PMID 29931526, 2018). "It has been reported recently that FGFR3 mutations are frequently found in non‐CD8+ T‐cell‐inflamed MIBC, and it was proposed that the FGFR3 pathway could be targeted to overcome resistance and sensitise tumours to PD‐1/PD‐L1 immunotherapy." (PMID 30043421, 2018). "We surmised that the compensatory induction of tumor barriers via an overexpression of tumor suppressor genes may contribute to the lack of tumorigenicity by the FGFR3 mutation, and therefore surveyed a number of such targets using real-time quantitative PCR." (PMID 27157475, 2016).